STK32B (serine/threonine kinase 32B)
Synonyms: YANK2; STKG6; STK32; HSA250839
Tractability: Small molecule: a high-quality ligand is known; it belongs to a druggable protein family. PROTAC: a small molecule that binds it is known.
Target class: Kinase; AGC protein kinase YANK family; Enzyme; Protein Kinase; AGC protein kinase group
Gene: Protein-coding gene on chromosome 4 (5,051,480 to 5,500,994, forward strand). Ensembl gene ENSG00000152953.
Subcellular location (Human Protein Atlas): Nuclear bodies; Nucleoplasm; Cytosol
Gene Ontology:
Molecular function: protein serine kinase activity; protein serine/threonine kinase activity; ATP binding; protein kinase activity
Biological process: intracellular signal transduction
Genetic constraint (gnomAD): Loss-of-function variants: 47 observed, 56.7 expected, observed/expected ratio (o/e) 0.83, 90% interval 0.65 to 1.06. The upper end of that interval is the gene's LOEUF score, 1.06, which puts it in group 4 of 6, group 1 being the genes least tolerant of losing a copy. Missense variants: 621 observed, 552.32 expected, observed/expected ratio (o/e) 1.12, 90% interval 1.05 to 1.2. Synonymous variants: 238 observed, 211.7 expected, observed/expected ratio (o/e) 1.12, 90% interval 1.01 to 1.25.
Homologues: Orthologues: chimpanzee STK32B (99% identical), macaque STK32B (97% identical), pig STK32B (93% identical), dog STK32B (93% identical), mouse Stk32b (92% identical), rat Stk32b (91% identical), rabbit STK32B (86% identical), guinea pig STK32B (85% identical), tropical clawed frog stk32b (81% identical), Drosophila melanogaster CG32944 (51% identical), Caenorhabditis elegans M03C11.1 (40% identical), zebrafish stk32a (32% identical), and 4 more. Paralogues in human: STK32A (66% identical), STK32C (65% identical), MAST2 (33% identical), MAST3 (32% identical), MAST1 (32% identical), MAST4 (31% identical), SGK2 (26% identical), LATS1 (26% identical), LATS2 (26% identical), SGK1 (25% identical), SGK3 (25% identical), MASTL (24% identical), and 1 more.
Diseases named in the same sentence as STK32B in open-access papers:
STK32B is named in the same sentence as 20 diseases in open-access papers, as found by Europe PMC text mining. Sharing a sentence is not in itself a finding about the gene and the disease. The quoted sentences say what the papers report.
essential tremor (5 papers, 2018 to 2024). A relatively common disorder characterized by a fairly specific pattern of tremors which are most prominent in the upper extremities and neck, inducing titubations of the head. "This variant is associated with the umbilical cord complications, and the most likely causal gene, STK32B, is reported to be associated with a variety of pregnancy-unrelated traits, such as essential tremor." (PMID 32403311, 2020). "STK32B is a serine/threonine kinase and resides at a locus previously identified in a GWAS for essential tremor." (PMID 32400971, 2020). "Genes such as LINGO1 rs9652490 and STK32B rs10937625 may influence the incidence of essential tremor." (PMID 36258958, 2022).
breast carcinoma (2 papers, 2010 to 2014). "DTL, ECT2, MTDH, PRC1 and RFC4 have all been previously implicated in breast cancer; SCUBE2 and STK32B deletions have been found to be related to mental deficits in humans; and ZNF533 has been found to be associated with the Hedgehog signaling pathway in Zebrafish." (PMID 20584321, 2010). "CBX2 plays a role in epigenetic regulation and hematopoietic stem cell differentiation, whereas the STK32B gene is one of several serine/threonine kinases (STK32B, STK36, and STK39) with similar gene expression patterns in basal-like breast cancers." (PMID 24885002, 2014).
Ellis-van Creveld syndrome (2 papers, 2022 to 2023). Ellis-van Creveld syndrome (EVC) is a skeletal and ectoderlam dysplasia characterized by a tetrad of short stature, postaxial polydactyly, ectodermal dysplasia, and congenital heart defects. "Within this deletion resides the developmental gene STK32B, which has been associated with Ellis-van Creveld syndrome, an autosomal-recessive skeletal dysplasia with co-occurring genital anomalies, e.g., hypospadias." (PMID 36319675, 2023). "The Stk32b gene is annotated into the “Sweet Taste Signaling” pathway, and deletion of the gene was associated with Ellis-Van Creveld Syndrome in humans." (PMID 34791189, 2022). "Furthermore, we detected a heterozygous deletion in Individual 8 comprising STK32B, which has been associated with Ellis-van Creveld syndrome, an autosomal-recessive skeletal dysplasia with co-occurring genital anomalies, e.g., hypospadias." (PMID 36319675, 2023).
Alzheimer disease (1 paper, 2023). A progressive, neurodegenerative disease characterized by loss of function and death of nerve cells in several areas of the brain leading to loss of cognitive function such as memory and language. "The female-biased genes in four regions were enriched for Alzheimer’s disease progression (SYN3 and STK32B) and the male-biased genes in four brain regions were enriched for neuroticism (PAX6 and PLTP)." (PMID 37221602, 2023).
Parkinson disease (1 paper, 2018). A progressive degenerative disorder of the central nervous system characterized by loss of dopamine producing neurons in the substantia nigra and the presence of Lewy bodies in the substantia nigra and locus coeruleus. "STK32B and CTNNA3 are two protein-coding genes, but the current study has not found any association with pathogenic pathways of Parkinson's disease." (PMID 29899728, 2018).
tumor (4 papers, 2014 to 2024). "However, expression of only one gene, encoding serine/threonine kinase 32B (Stk32b), differed significantly between Msx1 wt and Msx1-deficient tumor tissue." (PMID 30733598, 2019). "In a correlation analysis between protein expression patterns and established clinicopathological features, a clear link was found between CBX2-positivity and tumor inflammatory infiltration as well as STK32B-positivity and small tumor size (T1-T2)." (PMID 24885002, 2014). "Examples are COL4A6, WNK2 and STK32B whose roles have been assigned in processes such as prevention of early invasion stages, negative regulation of epidermal growth factor receptor signaling and opposite correlation with tumor size, respectively." (PMID 33691672, 2021). "In addition, SCUBE2 was significantly associated with lymph node status (P = 0.01), CBX2 with tumor inflammatory infiltration (P = 0.03), and STK32B with tumor size (P = 0.04)." (PMID 24885002, 2014). "We found that CBX2, SCUBE2, and STK32B protein expression were associated with important clinicopathological features for OSCC (peritumoral inflammatory infiltration, metastatic spread to the cervical lymph nodes, and tumor size)." (PMID 24885002, 2014).
cancer (3 papers, 2014 to 2024). A tumor composed of atypical neoplastic, often pleomorphic cells that invade other tissues. "Among the top downregulated 50 genes, there were other cancer relevant genes such as cell cycle associated (CCNF1, CCNB1, ZWINT), cancer signaling (STK32B, IGF1, FLT1) and splicing associated (HNRNPM, HNRNPU, SRSF1) genes, which are active areas to investigate further." (PMID 38200580, 2024). "Consequently, SCUBE2 and STK32B are involved in the hedgehog signaling pathway which plays a pivotal role in metastasis and angiogenesis in cancer." (PMID 24885002, 2014).
STK32B also shares sentences with these, for which no sentence is quoted: generalised anxiety disorder (2 papers); adrenocortical cancer (1); Anxiety (1); brain tumor (1); glioma (1); hepatocellular carcinoma (1); Hurler syndrome (1); hypospadias (1); invasive breast carcinoma (1); neurological disorders (1); oral squamous cell carcinoma (1); skeletal dysplasia (1); skin cancer (1).